BRCA2 (BRCA2 DNA repair associated)
Diseases named in the same sentence as BRCA2 in open-access papers (continued):
Sharing a sentence is not in itself a finding about the gene and the disease.
T-cell non-Hodgkin lymphoma (1 paper, 2007). A non-Hodgkin lymphoma of T-cell lineage. "Deleterious BRCA2 sequence variants are over-represented in cases of T-cell Non-Hodgkins lymphoma (NHL) or CLL, consistent with a role for BRCA2 in preventing these diseases." (PMID 17683622, 2007).
thoracic cancer (1 paper, 2023). A primary or metastatic malignant neoplasm affecting the tissues of the thorax. "Among the thoracic cancer cohort, only one patient exhibited concurrent high HRD score and SBS3, and this patient harbored a BRCA2 mutation that was classified as benign (T582P, clinvar variant accession VCV000037753.10)." (PMID 36964191, 2023).
thrombotic microangiopathy (1 paper, 2026). The syndromes of microangiopathic hemolytic anemia, thrombocytopenia, and variable signs of organ impairment, due to platelet aggregation in the microcirculation. "After one year of disease remission, he relapsed with bone marrow metastases, confirming the BRCA2 mutation, and presented with thrombotic microangiopathy (TMA)." (PMID 41669591, 2026).
uterine carcinosarcoma (1 paper, 2023). A usually aggressive malignant neoplasm arising from the uterine corpus and less often the cervix. "Only two patients tested were found to have a mutation in a BRCA gene (20%), and one of these was a patient with uterine carcinosarcoma, who was found to have a variant of unknown significance in the BRCA2 gene, for a final pathogenic mutation rate of 10%." (PMID 37835384, 2023).
uterine disease (1 paper, 2022). "In a multivariate linear regression model, both BRCA2 homozygous deletion and uterine disease status were independently associated with increased gLOH." (PMID 35468996, 2022).
uterine endometrioid carcinoma (1 paper, 2022). "Only 3% were classified as variants of strong clinical significance in BRCA1 and BRCA2 of ovarian high-grade serous (HGSC) and uterine endometrioid carcinoma." (PMID 36010253, 2022).
X-linked disease (1 paper, 2011). X-linked form of disease. "Similar findings were reported for the BRCA1 and BRCA2 genes and even for genes involved in X-linked diseases although allelic drop-out is expected to be less severe in X-linked diseases due to hemizygosity of the mutant allele in the affected males." (PMID 22125493, 2011).
xeroderma pigmentosum group D (1 paper, 2023). Any xeroderma pigmentosum in which the cause of the disease is a mutation in the ERCC2 gene. "We investigated the role of DNA repair proteins breast cancer susceptibility 2 (BRCA2), xeroderma pigmentosum group D (XPD) and apurinic/apyrimidinic endodeoxyribonuclease 1 (APE1) in determining the risk for head and neck squamous cell cancer (HNSCC) in a case-control study from North-East India." (PMID 37113717, 2023).
xerostomia (1 paper, 2021). Dryness of the mouth resulting from reduced salivary secretion. "Genetic alterations in BRCA2, ERBB3, NOTCH1 and CCND1 were all associated with higher mean grade of toxicity with BRCA2 alteration implicated in all toxicity parameters evaluated including mucositis, early dysphagia, xerostomia and to a lesser extent, late dysphagia." (PMID 34001187, 2021). "Interestingly, we find that BRCA2 and ERBB3 combination appeared to exhibit an additive effect on total rtAEs with a twofold increase or more in early dysphagia, early xerostomia and late dysphagia, compared to ERBB3 alteration alone." (PMID 34001187, 2021). "Interestingly, patients who exhibited alterations in both BRCA2 and ERBB3 experienced a twofold or greater increase in early dysphagia, early xerostomia and late dysphagia compared to ERBB3 alteration alone." (PMID 34001187, 2021).
cancer (2,434 papers, 1997 to 2026). A tumor composed of atypical neoplastic, often pleomorphic cells that invade other tissues. "We assessed this in detail for 59 families who had a secondary finding of BRCA1- or BRCA2-related cancer predisposition." (PMID 41950923, 2026). "A recent meta-analysis of 21 studies that addressed prophylactic interventions (chemoprevention and RRS) for healthy women with BRCA1 or BRCA2 variants, focused on both cancer risk reduction and mortality outcomes." (PMID 41488281, 2026). "Germline loss-of-function mutations in BRCA1 and BRCA2 markedly increase susceptibility to breast, ovarian, and other cancers." (PMID 42274517, 2026). "BRCA1 mutation carriers typically develop cancer in their 30s–40s, while BRCA2 carriers peak later, in their 40s–50s." (PMID 41510186, 2026). "The use of PARP inhibitors (PARPi) has profoundly changed the treatment of BRCA1/BRCA2-mutated cancers." (PMID 42244520, 2026). "This is further supported by the finding of the group of Sharon Cantor and our data presented here, confirming the PARPi resistance when MDC1 was depleted in human MDA-MB-436 (BRCA1-mutated) and PEO1 (BRCA2-mutated) cancer cells." (PMID 41408464, 2026). "Germline pathogenic variants in BRCA1 and BRCA2 confer disproportionately elevated cancer risks in breast and ovarian tissues, yet the basis for this tissue specificity remains incompletely understood." (PMID 42079105, 2026). "Despite the established role of APOBEC3s in cancer evolution, their interplay with BRCA2 loss remains unexplored." (PMID 41162355, 2025). "Still, there are essential dissimilarities between BRCA1 and BRCA2 with regard to their biological functions, the spectrum of associated cancer types, and the nuances of tumor presentation." (PMID 40547808, 2025). "As discussed, defective BRCA1 and BRCA2 increase cancer risk in men and women due to increased genomic instability." (PMID 40429877, 2025). "Our work defines an ATR-independent, scaffolding role for the 9-1-1 complex in ssDNA gap protection, revealing a fundamental mechanism of replication stress tolerance and a new therapeutic vulnerability in BRCA2-deficient cancers." (PMID 41278922, 2025). "BRCA1-associated cancers exhibited higher nuclear and histological grades compared to BRCA2-associated cancers." (PMID 41083355, 2025). "Variants in HR genes, such as BRCA1 and BRCA2 are known to increase cancer risk, particularly for breast and ovarian cancers." (PMID 40047910, 2025). "Like those with BRCA1 mutations, people with BRCA2 mutations are more likely to develop these cancers than the general population." (PMID 40141415, 2025). "Approximately 10% of patients with aggressive PC carry germline pathogenic variants in genes with established roles in cancer predisposition (BRCA2, ATM, CHEK2, NBN, BRCA1, PALB2, BRIP1, BARD1)." (PMID 41465280, 2025). "The corresponding posts are ‘live updates’ of the creator’s ongoing attempts of in vitro fertilisation (IVF) and preimplantation genetic testing (PGT) following the death from cancer of her late husband, a BRCA2 mutation carrier." (PMID 39302032, 2025). "In cancers where HR repair is impaired, such as those harboring mutations in BRCA1 and BRCA2 genes, cancer cells heavily rely on alternative DNA repair mechanisms, such as base excision repair (BER), to counteract DNA damage." (PMID 40574045, 2025). "Poly (ADP-ribose) polymerase inhibitors (PARPi) exploit DNA repair deficiency in germline BRCA1 and BRCA2 pathogenic variant (gBRCAm) cancers." (PMID 40360463, 2025). "Mutations affecting the interaction between BRCA2 and RAD51, such as those in the BRC repeats or the C‐terminal region of BRCA2, lead to impaired HR and increased cancer susceptibility." (PMID 40523654, 2025).
cancer (continued). "From a therapeutic standpoint, our findings position the 9-1-1 complex as a compelling target in BRCA2-deficient cancers." (PMID 41278922, 2025). "Genetic mutations are only counted in 5%–10% of cases of BC development, and BRCA1 and BRCA2 are important genes associated with cancer progression." (PMID 40755497, 2025). "PARP inhibitors (PARPi) have significantly advanced the treatment of cancers harboring BRCA1 or BRCA2 mutations by exploiting deficiencies in homologous recombination-mediated DNA repair." (PMID 41347092, 2025). "For carriers of BRCA2 PVs, cancer risk assessment should extend beyond the core HBOC cancers to include six additional cancer types." (PMID 40462315, 2025). "At the same time, somatic missense, indels, and deep intronic variants in genes such as BRCA1, BRCA2, and others involved in HR repair have been associated with cancer and treatment resistance." (PMID 40146757, 2025). "Utilizing a large population based cohort with extensive genetic data and information on the diagnosis of all common cancers, we obtained several pieces of evidence for BRCA2‐associated cancers." (PMID 40462315, 2025). "We then investigated the association of six BRCA1 and BRCA2 founder mutations with the risk of DCIS using 4702 cancer-free women as a reference group." (PMID 40002208, 2025). "In humans, mutations in the BRCA2 gene predispose to a high risk of developing breast, ovarian, and other types of cancers." (PMID 40923759, 2025). "pCRs were observed in 38/69 (55%) BRCA1 mutation carriers vs. 13/36 (36%) BRCA2-associated cancers (Fisher’s exact test, two-tailed, P = 0.1) or 43/150 (29%) BRCA-WT tumors (Fisher’s exact test, two-tailed, P = 0.0003)." (PMID 40547808, 2025). "This variant compromises the DNA repair pathway, a hallmark of BRCA2-related cancers, and appears to drive significant ECM remodeling." (PMID 40076915, 2025). "The risk of developing breast, ovarian, and other cancers is greatly increased by mutations in BRCA2." (PMID 40141415, 2025). "The therapeutic landscape of cancer treatment has been profoundly influenced by targeting BRCA1 and BRCA2 mutations, leading to innovative approaches and advancements in cancer therapy." (PMID 40004231, 2025). "First, despite the large sample size of the UKB, the number of carriers of BRCA2 PVs remains limited, reducing the statistical power to detect associations for some rare cancer types." (PMID 40462315, 2025). "Genetic testing for germline mutations—particularly for the BRCA1 and BRCA2 genes—is a key component of hereditary cancer risk assessment and its results can influence treatment choices, preventive interventions, and family-based cascade testing." (PMID 40710012, 2025). "Pathogenic mutations in exon 22 of BRCA1 and exon 27 of BRCA2 disrupt DNA repair mechanisms, leading to genomic instability and increased risk of cancer and progression." (PMID 40725150, 2025). "U. dioica significantly suppressed the expression of Brca1, Brca2, Fas, Lpl, Dgat1 and Mcp1 genes, resulting in significant changes in lipid metabolism, cancer susceptibility and inflammation." (PMID 40153121, 2025). "The accumulation of these DNA DSBs results in cell death specifically in DNA DSB repair-deficient cancer cells carrying BRCA1 or BRCA2 mutations through synthetic lethality." (PMID 40308947, 2025). "Like BRCA2, this mutation also correlates with more aggressive cancer phenotypes and poorer outcomes." (PMID 41541272, 2025). "Of these, 103 patients (8.6% of the total sample) carried germline pathogenic variants in genes that have been definitively linked to an increased risk of PC or other types of cancers (BRCA2, ATM, CHEK2, NBN, BRCA1, PALB2, BRIP1 and BARD1)." (PMID 41465280, 2025). "Specifically, this was shown for BRCA2 secondary mutations, which re-establish full length wild-type genes in tumors and promote cancer cell survival." (PMID 40002276, 2025).
cancer (continued). "The objectives of this study were to systematically assess the spectrum of BRCA2‐associated cancers and estimate the penetrance of BRCA2 PVs for these cancers in a large population based cohort, both independently and jointly with PGS." (PMID 40462315, 2025). "This study aimed to translate, culturally adapt and pilot-test a German version of the 8-item Cancer Worry Scale in individuals carrying BRCA1 or BRCA2 pathogenic variants in Austria." (PMID 40390061, 2025). "BRCA2-associated HGSOCs had a significantly higher rate of pCRs as compared to BRCA1-mutated cancers [8/15 (53%) vs. 7/48 (15%), Fisher’s exact test, two-tailed, P = 0.004]." (PMID 40547808, 2025). "In cells with BRCA1 or BRCA2 mutations, which cannot repair double-strand breaks already by homologous recombination, this accumulation of DNA damage becomes lethal, causing cancer cell death." (PMID 40004231, 2025). "In contrast, BRCA2 mutations are associated with an increased risk of developing cancers of the breast, prostate, pancreas, and skin in men." (PMID 40429877, 2025). "Higher fat mass was significantly associated with BRCA‐related cancer, with greater effect in BRCA2‐positive women." (PMID 40523654, 2025). "As there were differences in the number of variants in BRCA1 and BRCA2, gender ratios, and cancer types, we compared these outcomes separately." (PMID 40249378, 2025). "The high frequency of pathogenic BRCA2 mutations within the canonical DBD in cancer patients underscores the importance of ssDNA binding of BRCA2 in vivo." (PMID 40923759, 2025). "BRCA2 PVs increase risk beyond core HBOC cancers and their risks are modified by cancer‐specific PGS." (PMID 40462315, 2025). "BRCA2-deficient cancer exhibits heightened sensitivity to TPX2 and AurkA inactivation through alisertib treatment, which delays mitotic progression." (PMID 40362354, 2025). "For instance, BRCA2-deficient cancer cells are more dependent on PARP1 to repair DNA for survival, resulting in an increased sensitivity to PARP1 inhibitors, which kill the cancer cells through the genetic concept of synthetic lethality." (PMID 40362634, 2025). "It is through HRD that BRCA1 and BRCA2 carriers are thought to be at an increased risk for various cancers." (PMID 41256354, 2025). "Almost 5%–10% of cases of BC are due to genetic mutations, and BRCA1 and BRCA2 are important genes associated with cancer progression." (PMID 40761498, 2025). "Pathogenic/likely pathogenic (P/LP) germline variants (PGVs) in cancer-predisposing genes, mostly in BRCA1 and BRCA2 have been linked to the etiology of breast and many other cancers." (PMID 41568010, 2025). "Germline BRCA1 and BRCA2 testing is a standard evidence-based practice, with established risk reduction and cancer screening guidelines for genetic carriers." (PMID 40853717, 2025). "The remaining eight participants had their P/LP variants validated at the HMC laboratory (five GPPs in BRCA1 and three GPPs in BRCA2) and were referred to the cancer genetics and high-risk surveillance program." (PMID 41463058, 2025). "This review aims to expand the discussion of BRCA1 and BRCA2 beyond their association with CMTs, exploring their broader implications in the oncogenesis of various dog cancers." (PMID 40004231, 2025). "Having observed killing of engineered BRCA2-deficient cells, we next investigated the sensitivity of cancer cell lines with mutations in BRCA1." (PMID 41359388, 2025). "Single-cell RNA-sequencing approaches will reveal BRCA2-associated variant transcriptomes resulting from differential splicing in a manner specific to mutation, cell, and cancer types." (PMID 40724944, 2025).
cancer (continued). "Yet, the precise connection between their DNA repair functions and their capabilities in processing R-loops, particularly in the context of cancer-associated mutations in BRCA1/BRCA2, remains elusive." (PMID 40271193, 2025). "The aim of this study was to evaluate trends in utilization of BRCA1 and BRCA2 testing in Ontario since the inception of this program and to identify gaps in testing in order to inform targeted strategies for cancer risk reduction." (PMID 40862808, 2025). "Mutations in the BRCA1 and BRCA2 genes lead to chromosomal instability and increase the risk of having cancer, accounting for 3%–8% of BC cases and 30%–40% of HBC cases." (PMID 41049353, 2025). "While intratumoral heterogeneity has already been demonstrated in BRCA1-related tumors, its involvement in the pathogenesis of BRCA2-associated cancers requires additional studies." (PMID 40547808, 2025). "We first showed that the spectrum of BRCA2‐associated cancers is not limited to core HBOC cancers but includes six additional types of cancer." (PMID 40462315, 2025). "Studies reveal a correlation between BRCA2 mutations and various other cancer types, such as pancreatic and prostate cancers." (PMID 40141415, 2025). "BRCA1 and BRCA2 are among the most studied cancer susceptibility genes, significantly increasing the risk of breast, ovarian, pancreatic and prostate cancers." (PMID 40943312, 2025). "For each individual cancer type, carriers of BRCA2 PVs were significantly associated with increased risk for each of the four core HBOC cancers." (PMID 40462315, 2025). "This is the first study analyzing the immediate outcomes of NACT in BRCA1- vs. BRCA2-associated cancers." (PMID 40547808, 2025). "Cyclin D1 expression, which has an estrogen induction, was less frequent in BRCA1 than in BRCA2-mutated carcinomas, with gene amplification rates of 18% in BRCA1 and 60% in BRCA2." (PMID 40136510, 2025). "Several high‐penetrance mutations have been shown to exhibit pleiotropy across multiple cancers; for example, BRCA2, a gene involved in DNA repair, has been implicated in cancers of the breast, ovary, pancreas, and prostate." (PMID 39606803, 2024). "Genetic testing of the BRCA1 and BRCA2 gene mutations is particularly recommended for individuals with familial susceptibility to cancer or who have a personal history of cancer." (PMID 38785549, 2024). "Cells deficient in breast cancer gene 1 or 2 (BRCA1 or BRCA2) function have a high level of chromosomal instability." (PMID 39085400, 2024). "For BRCA1 and BRCA2 carriers, the finding of a mutation has clear implications for cancer management, but for other genes, such as ATM, the management implications are less clear." (PMID 39543654, 2024). "CX-5461, also known as pidnarulex, is a strong G4 stabilizer and has received FDA fast-track designation for BRCA1- and BRCA2- mutated cancers." (PMID 39027314, 2024). "Research has suggested a potential link between these cancers and BRCA2 mutations, influencing risk, survival, and age of onset." (PMID 39001408, 2024). "Women who carry a BRCA1 or BRCA2 mutation have elevated risks for many types of cancer, including breast, ovarian, fallopian tube and peritoneal cancers." (PMID 38741145, 2024). "The inherited heterozygous deficiency of BRCA1 or BRCA2 increases the risk of breast, ovarian, and other cancers due to aberrant DNA repair." (PMID 38398147, 2024). "Only BRCA2 was found to have a high recurrent number of missense mutations in fishing cats diagnosed with TCC when compared to inherited human cancer risk variants." (PMID 38580653, 2024). "One prospective, multicenter study included 2482 women with BRCA1 or BRCA2 P/LP variants from 22 centers in Europe and North America to assess the relationship of risk-reducing mastectomy or salpingo-oophorectomy with cancer outcomes." (PMID 39507757, 2024). "BRCA1/BRCA2-associated cancers are characterized by genomic instability, leading to large-scale copy number alterations." (PMID 39198848, 2024).